CSF3R (colony stimulating factor 3 receptor)
Description:
Receptor for granulocyte colony-stimulating factor (CSF3), essential for granulocytic maturation. Plays a crucial role in the proliferation, differentiation and survival of cells along the neutrophilic lineage. In addition it may function in some adhesion or recognition events at the cell surface.
Synonyms: G-CSF-R; CD114; GCSFR; SCN7
Tractability: Antibody: UniProt places it where antibodies can reach, with high confidence; its Gene Ontology location is reachable by antibodies, with high confidence; UniProt predicts a signal peptide or a membrane-spanning region. PROTAC: ubiquitination databases record sites on it. Other modalities: an approved drug acts on it.
Target class: Membrane receptor
Gene: Protein-coding gene on chromosome 1 (36,465,669 to 36,483,322, reverse strand). Ensembl gene ENSG00000119535.
Subcellular location: Secreted (Isoform 2); Cell membrane
Pathways (Reactome):
Immune System: Inactivation of CSF3 (G-CSF) signaling; Other interleukin signaling; Signaling by CSF3 (G-CSF)
Developmental Biology: Transcriptional regulation of granulopoiesis
Gene Ontology:
Molecular function: protein binding; cytokine binding; cytokine receptor activity; signaling receptor activity; granulocyte colony-stimulating factor binding
Biological process: cytokine-mediated signaling pathway; defense response; positive regulation of cell population proliferation; signal transduction; amelogenesis
Cellular component: endocytic vesicle membrane; external side of plasma membrane; lysosomal membrane; plasma membrane; receptor complex; extracellular region; membrane
Genetic constraint (gnomAD): Loss-of-function variants: 52 observed, 90.28 expected, observed/expected ratio (o/e) 0.58, 90% interval 0.46 to 0.73. The upper end of that interval is the gene's LOEUF score, 0.73, which puts it in group 2 of 6, group 1 being the genes least tolerant of losing a copy. Missense variants: 889 observed, 1,108.5 expected, observed/expected ratio (o/e) 0.8, 90% interval 0.76 to 0.85. Synonymous variants: 384 observed, 453.81 expected, observed/expected ratio (o/e) 0.85, 90% interval 0.78 to 0.92.
Cancer hallmarks: invasion and metastasis (promotes); escaping programmed cell death (promotes); proliferative signalling (promotes)
Homologues: Orthologues: chimpanzee CSF3R (99% identical), macaque CSF3R (94% identical), dog CSF3R (77% identical), pig CSF3R (76% identical), rabbit CSF3R (75% identical), guinea pig CSF3R (73% identical), rat Csf3r (64% identical), mouse Csf3r (63% identical), tropical clawed frog csf3r (32% identical), zebrafish csf3r (26% identical). Paralogues in human: IL12RB2 (23% identical), IL6ST (19% identical), LIFR (17% identical), IL27RA (17% identical), IL31RA (16% identical), OSMR (16% identical), LEPR (13% identical), IL23R (12% identical), IL12RB1 (11% identical), CRLF1 (10% identical), IL11RA (10% identical), PRLR (10% identical), and 11 more.
Diseases named in the same sentence as CSF3R in open-access papers:
CSF3R is named in the same sentence as 180 diseases in open-access papers, as found by Europe PMC text mining. Sharing a sentence is not in itself a finding about the gene and the disease. The quoted sentences say what the papers report.
chronic neutrophilic leukemia (42 papers, 2014 to 2025). A rare chronic myeloproliferative neoplasm characterized by neutrophilic leukocytosis. "CSF3R has been directly implicated as a causal gene for chronic neutrophilic leukemia and atypical chronic myloid leukemia, and has also been associated with neutropenia (insufficient neutrophils)." (PMID 41345545, 2025). "Somatic activating CSF3R mutations are highly associated with chronic neutrophilic leukemia (CNL) and present with neutrophilia, hypercellular bone marrow with granulocytic proliferation, and the absence of dysplasia or increased blasts." (PMID 40806796, 2025). "Driver mutations in CSF3R gene represent a diagnostic marker of chronic neutrophilic leukemia (CNL)." (PMID 39907800, 2025). "Mutations in CSF3R are common in patients with chronic neutrophilic leukemia or atypical chronic myeloid leukemia, and this gene has been also detected under positive selection in four long‐lived mammals (LRT p value = 5.00 × 10−4)." (PMID 37395176, 2023). "A single amino acid mutation in CSF3R, T618I, instead allows for constitutive, ligand-independent cell growth and leads to a rare type of cancer called chronic neutrophilic leukemia." (PMID 37116708, 2023). "Chronic neutrophilic leukemia (CNL) relates to mutational CSF3R activation with membrane proximal CSF3R mutations such as T618I as driver mutations, but the significance of truncating mutations is not clarified." (PMID 35200567, 2022). "Activating CSF3R mutations have been found in the majority of chronic neutrophilic leukemias (CNLs)." (PMID 33909614, 2021). "CSF3R mutations are a hallmark of chronic neutrophilic leukemia (CNL), a rare MPN defined by persistent mature neutrophilic leukocytosis." (PMID 33516272, 2021). "Mutation of Csf3r activates the receptor and promotes neutrophil proliferation, leading to chronic neutrophilic leukemia." (PMID 33828460, 2021). "A mutation in CSF3R has been implicated in neutrophilic leukemia, characterized by increased neutrophils, and severe bleeding." (PMID 30836997, 2019). "CSF3R mutations are associated with chronic neutrophilic leukemia (defined by an abundance of mature neutrophils) yet also accelerate AML formation in the context of mutant CEBPA." (PMID 31784538, 2019). "CSF3R mutations are associated with response of chronic neutrophilic leukemia to JAK inhibitors such as ruxilitinib and provide another possible avenue for targeted therapy in ETP-ALL." (PMID 27148573, 2015). "This mutation has been described in a high fraction of chronic neutrophilic leukemia and produces constitutive activation of CSF3R (also known as the G-CSF receptor)." (PMID 27148573, 2015). "Some studies have also suggested that CSF3R mutations may be effective diagnostic and prognostic markers for chronic neutrophilic leukemia and chronic myeloid leukemia." (PMID 35909123, 2022). "Mutations in CSF3R have been linked to chronic neutrophilic leukemia." (PMID 36056316, 2022). "Driver mutations in CSF3R gene represent a specific diagnostic hallmark of chronic neutrophilic leukemia (CNL), a myeloproliferative neoplasm (MPN) defined by neutrophilia, hypercellular bone marrow and poor prognosis." (PMID 39907800, 2025). "While activating CSF3R mutations are characteristic of chronic neutrophilic leukemia (CNL), they are infrequent in de novo AML, occurring in 1%–3% of cases." (PMID 41423432, 2025). "Intriguingly, it was noted that not all patients in the CNL-like group carried mutant CSF3R (12 out of 26 with wild-type CSF3R), which may change future disease subtyping and/or treatment strategy for neutrophilic leukemia patients with a CNL-like expression signature instead of CSF3R mutations." (PMID 40255485, 2025). "According to the revision of the World Health Organization classification of myeloid neoplasms 2016, CSF3R mutations are strongly associated with chronic neutrophilic leukemia (CNL), however do also appear in atypical chronic myeloid leukemia (aCML)." (PMID 32660441, 2020).
chronic neutrophilic leukemia (continued). "Especially the role of mutations in the CSF3R gene, coding for the G-CSF receptor, in aCML were controversially discussed as CSF3R mutations are defining mutations in the diagnosis of chronic neutrophilic leukemia (CNL)." (PMID 32660441, 2020). "A peripheral blood search for the CSF3R mutation (T618I) was positive, also suggesting Chronic Neutrophilic Leukemia (CNL)." (PMID 33414971, 2020). "The mutation site of CSF3R in MDS patients was different from the known site of mutation in congenital neutropenia but two of the patients showed CSF3R mutation reported in myeloid neoplasms such as chronic neutrophilic leukemia or chronic myelomonocytic leukemia." (PMID 27465399, 2016). "While CSF3R mutations are rare in B-ALL, truncating and activating mutations in this gene are known drivers in chronic neutrophilic leukemia and atypical chronic myeloid leukemia." (PMID 41333018, 2025). "There are also rarer forms such as chronic neutrophilic leukemia (CNL), which involves mutations in the CSF3R gene." (PMID 38254802, 2024). "CSF3R mutations can be detected in approximately 80% of patients with chronic neutrophilic leukemia (CNL), and CSF3R mutations are now used as specific diagnostic molecular markers for CNL and atypical chronic myeloid leukemia (aCML)." (PMID 38629070, 2024). "At present, CSF3R research is mainly focused on its role in blood diseases, especially in the blood of patients with chronic neutrophilic leukemia." (PMID 37449204, 2023). "Chronic neutrophilic leukemia (CNL) is a myeloproliferative neoplasm characterized by the overproduction of neutrophils and activating mutations in CSF3R, the receptor for colony stimulating factor 3 (GCSF)." (PMID 35200567, 2022). "CSF3R is closely related to prognosis of patients with chronic neutrophilic leukemia or atypical chronic myeloid leukemia and thus represents a potentially useful criterion for disease diagnosis." (PMID 33692952, 2021). "Additionally, in a study on chronic neutrophilic leukemia (CNL) and atypical (BCR-ABL1–negative) CML in patients with CSF3R mutations, CSF3R truncating mutations were found to be sensitive to dasatinib suggesting that the trial of SRC kinase inhibitors is a reasonable approach." (PMID 34771705, 2021). "Mutations in CSF3R, SETBP1 and CALR are reported in patients with chronic neutrophilic leukemia (CNL)." (PMID 25316523, 2014). "In Chronic Neutrophilic Leukemia (CNL) and atypical Chronic Myeloid Leukemia (CML), many CSF3R oncogenic mutations have been reported to segregate to two distinct regions of CSF3R, leading to preferential downstream signaling pathways through the SRC family–TNK2 or JAK kinases." (PMID 34573308, 2021). "Chronic neutrophilic leukemia (CNL) is a rare myeloproliferative neoplasm that is genetically characterized by the absence of both the Philadelphia chromosome and BCR-ABL1 fusion gene and the high prevalence of mutations in the colony-stimulating factor 3 receptor (CSF3R)." (PMID 34068566, 2021). "Molecular studies, including polymerase chain reaction for colony stimulating factor 3 receptor (CSF3R) mutation and fluorescence in situ hybridization for the BCR::ABL1 fusion gene, were negative, effectively ruling out chronic neutrophilic leukemia and chronic myeloid leukemia, respectively." (PMID 40438677, 2025).
congenital neutropenia (31 papers, 2006 to 2025). "CSF3R truncation mutations are also prevalent in patients with severe congenital neutropenia (SCN), a condition with heterogenous basis often related to mutations in the ELANE gene encoding neutrophil elastase." (PMID 35200567, 2022). "The clinical characteristics and treatment of children with congenital neutropenia caused by biallelic CSF3R mutations in the literature." (PMID 34778134, 2021). "In a longitudinal study of colony-stimulating factor 3 receptor gene (CSF3R) mutations in congenital neutropenia, the independent acquisition of several different CSF3R mutations in different cells was demonstrated." (PMID 25056697, 2014). "CSF3R mutations were previously identified as oncogenic, and the T618I mutation has been identified to truncate the cytoplasmic tail of CSF3R, which is similar to CSF3R mutations that have been observed to progress congenital neutropenia to AML." (PMID 36497424, 2022). "High frequency of acquired CSF3R (colony stimulating factor 3 receptor, granulocyte) mutations has been described in patients with severe congenital neutropenia (CN) at pre-leukemia stage and overt acute myeloid leukemia (AML) or myelodysplastic syndrome (MDS)." (PMID 30891028, 2019). "It is well known that mutation of CSF3R is accompanied in congenital neutropenia." (PMID 27465399, 2016). "While CSF3R mutations are most commonly found in severe congenital neutropenia (SCN), the rates of CSF3R mutations rises sharply upon progression to secondary acute myeloid leukemia (sAML)." (PMID 28209919, 2017). "Besides, CSF3R has been linked to the developing congenital neutropenia." (PMID 20967291, 2010). "Similarly, in humans, single gene mutations have been described in both CSF3 and CSF3R resulting in severe congenital neutropenia (SCN)." (PMID 33236983, 2020). "This group includes congenital neutropenia caused by mutations in ELANE, GFI1, HAX1, WAS (X-linked neutropenia), CSF3R, and SRP54 genes." (PMID 31709206, 2019). "While CSF3R truncation mutations promote leukemic transformation in severe congenital neutropenia (SCN), their significance for CNL pathogenesis has not been fully clarified." (PMID 35200567, 2022). "CSF3R encodes the receptor for CSF3, a cytokine that controls the proliferation and differentiation of granulocytes, and is also mutated in a severe form of congenital neutropenia (MIM# 617014)." (PMID 28787443, 2017). "These csf3r mutants are a new animal model of human CSF3R-dependent congenital neutropenia." (PMID 28281657, 2017). "The congenital neutropenia patients that did not develop leukemia had an incidence of CSF3R mutation in 34 %, compared to 78 % for patients who showed transformation into acute leukemia." (PMID 27465399, 2016). "CSF3R mutations are found in many diseases other than CNL, including severe congenital neutropenia (SCN), which can play a driving role in the development of different myeloid neoplasms like acute myeloid leukemia." (PMID 39858009, 2025). "show that acquisition of a mutation in Cxxc4 results in increased CXXC4 protein levels, reduced TET2 protein, increased inflammatory signaling, and leukemic progression of a CSF3R/RUNX1 mutant mouse model of severe congenital neutropenia (SCN)." (PMID 33205068, 2020). "Our study highlights the significant presence of the CSF3R mutation across a diverse range of myeloid neoplasms, expanding their known spectrum beyond the traditional associations with CNL, aCML, and severe congenital neutropenia (SCN)." (PMID 40806796, 2025). "In addition to CNL, CSF3R alterations are frequently seen in atypical chronic myeloid leukemia (aCML), also known as myelodysplastic/myeloproliferative neoplasm with neutrophilia (MDS/MPN-N), and severe congenital neutropenia (SCN)." (PMID 40806796, 2025).
neutropenia (29 papers, 2010 to 2025). A decrease in the number of neutrophils found in the blood. "Accordingly, mouse model of truncated CSF3R mutations showed immature myeloid cells and mild neutropenia." (PMID 39907800, 2025). "Most truncating or missense mutations in the extracellular domain of CSF3R were reported to be loss-of-function alterations associated with neutropenia." (PMID 39907800, 2025). "Patients with CSF3R mutations frequently display full myeloid cell maturation in the bone marrow in spite of severe peripheral neutropenia." (PMID 39286252, 2024). "In this report, we describe the case of a 2-year old girl with recurrent infection and neutropenia who was genetically diagnosed with SCN7 caused by biallelic inactivating mutations in CSF3R." (PMID 34778134, 2021). "Genetic deficiency of the G-CSF-R (Csf3r−/−) caused a profound neutropenia in the peripheral blood of healthy mice." (PMID 31257026, 2019). "In summary, we have reported the establishment of sensitive CSF3R deep sequencing for assessing CSF3R mutation status in neutropenia patients." (PMID 30891028, 2019). "In summary, we have built a new animal model of severe congenital neutropenia due to CSF3R mutation." (PMID 28281657, 2017). "Thus, we hypothesize that in addition to the genetic predisposition of DARC, CSF3R can account for the observed differences in HIV induced neutropenia." (PMID 20967291, 2010). "Subsequently, infected csf3r morphants died between 2 and 3 dpi with overwhelming bacterial proliferation and neutropenia." (PMID 30016370, 2018). "Broadly, these conditions can be divided into those where neutropenia is the predominating feature, such as in ELANE, GFI1, HAX1, CSF3R and WAS mutations and those where neutropenia is part of a multi-system disorder." (PMID 23758768, 2013). "A previous report shows that patients with bialliac CSF3R deficiency can present mild neutropenia that does not require active treatment and suggests that other compensatory mechanisms are involved in the maintenance of adequate number of neutrophils." (PMID 34778134, 2021). "We found that acquisition of CSF3R mutations is a CN-specific phenomenon and is not present in patients with other types of neutropenia chronically treated with rhG-CSF." (PMID 30891028, 2019).